ENSG00000261832 (novel protein)
Gene: Protein-coding gene on chromosome 16 (28,456,371 to 28,492,098, reverse strand). Ensembl gene ENSG00000261832.
Genetic constraint (gnomAD): Loss-of-function variants: 14 observed, 18.55 expected, observed/expected ratio (o/e) 0.75, 90% interval 0.5 to 1.18. Missense variants: 109 observed, 134.15 expected, observed/expected ratio (o/e) 0.81, 90% interval 0.69 to 0.95. Synonymous variants: 52 observed, 51.65 expected, observed/expected ratio (o/e) 1.01, 90% interval 0.81 to 1.27.